CAT (catalase)
Diseases named in the same sentence as CAT in open-access papers (continued):
Sharing a sentence is not in itself a finding about the gene and the disease.
periodontitis (continued). "This study demonstrated that experimental periodontitis in rats leads to oxidative stress as indicated by a significant reduction in SOD and CAT levels in gingival tissue." (PMID 29249988, 2017). "To date, there are no publications that evaluated the effect of resveratrol on CAT gene expression and enzymatic activity in periodontitis; hence, this finding is yet to be discussed." (PMID 41395982, 2025). "Another study showed that the activities of antioxidant enzymes SOD, CAT, and glutathione reductase in saliva of periodontitis patients exhibited a significant negative correlation with periodontal parameters." (PMID 29180965, 2017). "Recent studies measured CAT and SOD activities in gingival tissues of patients with periodontitis." (PMID 25374447, 2014). "The beneficial effects of marigold were demonstrated in a study on experimental periodontitis in rats, where the administration of Calendula officinalis extract reduced OS in periodontal tissues by restoring the activity of antioxidant enzymes (GSH, SOD, CAT) and decreasing MDA levels." (PMID 40422642, 2025). "The results of this study showed that the regulatory effect of GLE’s ROS regulation and antioxidant enzyme proteins (SOD, CAT) was reversed by silencing 11β-HSD1, this suggests that GLE exerts an antioxidant effect through regulating 11β-HSD1 from oxidative stress generated by periodontitis." (PMID 40733170, 2025). "Their results showed a statistically significant decrease in total antioxidant capacity, superoxide dismutase, catalase, and glutathione peroxidase in patients with chronic periodontitis and ischemic heart disease with or without periodontitis compared to healthy patients." (PMID 36077473, 2022). "The experimental periodontitis caused significant reduction of the GSH, SOD and CAT, as well as an increase on MDA gingival levels (P < 0.05) when compared to the Naïve group, suggesting that oxidative stress is observed in gingival tissue subjected to periodontitis." (PMID 28701962, 2017). "The present study showed a statistically significant reduction in total antioxidant capacity, superoxide dismutase, catalase, and glutathione peroxidase in patients with chronic periodontitis and ischemic heart disease with or without periodontitis when compared to healthy patients." (PMID 28781595, 2017). "This was a case-control study on a sample of 150 non-smokers patients aged 30–60 years old from India, where the authors aimed to estimate the levels of glutathione, catalase, and Se in the serum of diabetic patients with periodontitis and healthy individuals with and without chronic periodontitis." (PMID 27617985, 2016). "In addition, periodontal tissues from clinically healthy patients (I) as well as from patients with the diagnosis of gingivitis (II) and periodontitis (III) were obtained from three different patients for each group and stained immunohistochemically for NOX4, CAT, and SOD." (PMID 25374447, 2014). "In the obligate anaerobic bacteria responsible for periodontitis, Tannerella forsythia and Porphyromonas gingivalis, both being catalase negative similar as X. nematophila, ahpC is positively expressed by OxyR and this may compensate for the absence of catalase activity in peroxide detoxification." (PMID 39058385, 2024). "Thus, the aim of this study was to investigate the total antioxidant capacity and levels of superoxide dismutase, glutathione peroxidase, and catalase in serum and saliva in chronic periodontitis patients with and without ischemic heart disease and to correlate the salivary and serum levels." (PMID 28781595, 2017). "Results of the serum estimation indicated that the levels of antioxidants (TAC, CAT, and GPx) were comparatively higher in the healthy group as compared to the other 3 groups with the least values observed in the ischemic heart disease group with and without periodontitis." (PMID 28781595, 2017).
Alzheimer disease (41 papers, 2013 to 2026). A progressive, neurodegenerative disease characterized by loss of function and death of nerve cells in several areas of the brain leading to loss of cognitive function such as memory and language. "Decreased levels and activity of antioxidants like SOD and CAT have also been linked to Alzheimer’s disease, according to several studies." (PMID 37368609, 2023). "Diminished catalase activity is associated with oxidative stress, aging, and Alzheimer’s disease." (PMID 37189641, 2023). "Additionally, improved depression-like behavior associated with Alzheimer’s disease was shown to be dependent on CAT level increase induced by DPZ administration." (PMID 32962160, 2020). "Inefficient RQC during APP synthesis generates CAT-tailed species that precipitate hallmarks of Alzheimer’s disease." (PMID 38311171, 2024). "Previous studies have demonstrated that Alzheimer’s diseases patients exhibit a low level of antioxidant enzymes, such as superoxide dismutase, catalase, peroxiredoxins, etc.." (PMID 33719938, 2021). "It has been demonstrated that SOD, CAT, and GPx specific activities, diminished in Alzheimer’s disease, are elevated with the use of antioxidants." (PMID 29875670, 2018). "Catalase activity is higher in the frontal cortex and plasma of patients with Alzheimer’s disease relative to controls." (PMID 23536801, 2013). "Similarly, catalase gene therapy has been found to attenuate oxidative damage and improve cognitive function in models of Alzheimer’s disease." (PMID 37760929, 2023). "TMDC NZ with CAT-/SOD-like activity was used to mitigate the pathology of Alzheimer’s disease by targeting neuronal mitochondria with (3-carboxypropyl)triphenyl-phosphonium bromide-conjugated 1,2-distearoyl-sn-glycero-3-phosphoethanolamine-N-[amino(PEG)-2000]-functionalized MoS2 QDs." (PMID 35009484, 2022). "CAT erythrocyte activity and concentration of plasma UA were significantly higher (↑27% p = 0.0222, ↑28% p ≤ 0.0001, respectively) in the group of patients with Alzheimer’s disease compared to the control group." (PMID 34903846, 2021). "Nevertheless, despite these observations, other studies do not support the idea of CAT being a susceptibility factor for Alzheimer’s disease, Parkinson’s disease, or familial amyotrophic lateral sclerosis." (PMID 31357514, 2019). "Therefore, catalase has both a direct and an indirect relationship with the pathogenesis of Alzheimer's disease." (PMID 31827713, 2019). "Therefore, catalase has a direct relationship with the pathogenesis of Alzheimer's disease." (PMID 41080744, 2025). "Several previous studies indicated that after morphine exposure, the activity of SOD and CAT enzymes was decreased, Additionally, MPO has been linked to neurological diseases, with significantly higher peripheral blood concentrations observed in Alzheimer's disease patients." (PMID 41404029, 2025). "Similarly, GPx, which converts lipid peroxides into less harmful alcohols and reduces hydrogen peroxide to water, and CAT, which protects SOD by converting hydrogen peroxide to water and oxygen, are also linked to neurodegenerative conditions like Alzheimer's disease." (PMID 39628974, 2024). "In addition, there is compelling evidence that binding of the neurotoxic β-amyloid peptide to CAT decreases its activity, a phenomenon that may explain why CAT activity is reduced in the brain of Alzheimer’s disease patients." (PMID 31357514, 2019). "Similarly, a previous investigation revealed that HupA could diminish the production of MDA and augment the activities of anti-oxidant enzymes including GSH-PX and CAT in an APP/PS1 mouse model of Alzheimer’s disease." (PMID 24857910, 2014). "In Alzheimer’s disease models, it also upregulates endogenous antioxidative enzymes such as SOD and catalase, mitigating amyloid-β-induced oxidative injury." (PMID 40963932, 2025).
Alzheimer disease (continued). "In a mouse model of Alzheimer’s disease, CV has been shown to improve spatial memory by activating antioxidants such as superoxide dismutase (SOD) and catalase (CAT) and inhibiting pro-inflammatory cytokines." (PMID 35204289, 2022). "Such a decline increases the vulnerability of the brain to the deleterious effects of oxidative damage; the brains of patients with Alzheimer's disease showed reduced activity of antioxidant enzymes (SOD, catalase, glutathione peroxidase and glutathione reductase)." (PMID 33103041, 2020). "Indeed, catalase overexpression in mitochondria is effective not only in delaying AHL, but also preventing dementia in Alzheimer’s disease model mice by neuroprotection." (PMID 32423039, 2020). "It has previously been shown that pelargonidin could significantly attenuate MDA and catalase activity in the hippocampus, decrease glial fibrillary acidic protein (GFAP) levels, and thereby improve memory and learning functions in a rat model of Alzheimer’s disease." (PMID 33552591, 2021).
gastric ulcer (40 papers, 2007 to 2025). An ulcerated lesion in the mucosal surface of the stomach. "Petroleum ether and methanol fruit extracts increased in catalase (CAT) levels in gastric ulcer rats." (PMID 34925698, 2021). "Effects of Raspberry Ketone on reduced GSH, lipid peroxides (TBARs), GPX activity, and catalase in ethanol-induced gastric ulcer in rats." (PMID 31404064, 2019). "Pretreatment with the M. quadrangula extract decreased lipid peroxidation and increased the antioxidant enzymes SOD and CAT in the stomach of a rat model of ethanol-induced gastric ulcer." (PMID 30363969, 2018). "In the present study, the defense role played by endogenous antioxidant enzymes particularly SOD and CAT on the gastric ulcer tissue was studied." (PMID 29121900, 2017). "In addition, crucial internal antioxidant enzymes, particularly SOD, CAT, and GPx, play a vital role in preventing the development of gastric ulcers." (PMID 40931332, 2025). "The gastric ulcer caused by ethanol is related to high production of reactive oxygen species (ROS), which can trigger oxidative stress by inhibiting the effects of antioxidants including glutathione (GSH), superoxide dismutase (SOD), and catalase (CAT)." (PMID 30643529, 2018). "As previously reported, Nigella sativa L. seed aqueous extract enhances gastric ulcer healing by boosting antioxidant enzymes (SOD, CAT, GPx), restoring gastric mucus and NP-SH levels, and protecting the mucosa from oxidative damage." (PMID 41357879, 2025). "The present data showed noticeable antioxidant potentials of PAG represented by up‐regulation of SOD, CAT, and PGE2 and reduced MDA levels in the gastric homogenates of rats ingesting ethanol as gastric ulcer inducers." (PMID 40034223, 2025). "For example, studies showed that Dioscorea administration in ethanol-induced gastric ulcer models significantly increased the activity of antioxidant enzymes such as SOD, GPx, and CAT, while reducing pro-inflammatory cytokines like TNF-α, IL-1β, and IL-6." (PMID 41010469, 2025). "Biochemical evaluation of oxidative stress enzymes revealed an increase in the SOD, CAT and GSH levels and a decrease in the MDA levels in the indomethacin-induced gastric ulcer group." (PMID 39861070, 2024). "The objective of this study was to determine the effect of a water extract of the MN plant on indomethacin-induced gastric ulcer in rats, using a series of biochemical (SOD, CAT, GSH and MDA levels) and histopathological parameters." (PMID 39861070, 2024). "The antioxidant levels (SOD, GSH, GPx, catalase, and MDA) in the stomach tissue homogenates were evaluated to examine the effect of antioxidant defenses on the gastric ulceration (GU) process." (PMID 38342928, 2024). "In rats, AST pretreatment (5 or 25 mg/kg BW; three days) significantly increased the activity of anti-oxidant enzymes such as SOD, CAT, and GPX in response to the ethanol-induced gastric ulcer." (PMID 36555112, 2022). "In rats, the intake of alcohol to induce a gastric ulcer increased the expression of cyclooxygenase-2 mRNA and decreased GPx, SOD, and CAT, but the intake of hesperidin reversed these changes, improving the antioxidant and inflammatory status." (PMID 33799833, 2021). "Pretreatment with 5 × 108 cfu/mL CB decreases the content of MDA in the serum of mice suffering from gastric ulcer and improves the activities of SOD and CAT in gastric tissue." (PMID 34336091, 2021). "In the naproxen-induced gastric ulcer model in rats, pretreatment with 20, 50, and 80 mg/kg anthocyanins twice daily for 3 days reduced gastric MDA levels and increased CAT and SOD activity." (PMID 33050668, 2020). "The present study provides convincing evidence that CNCP possesses gastroprotective activity in gastric ulcer models via the pathways, leading to the increase of the levels of mucus and PGE2, as well as the activities of SOD and CAT." (PMID 31889181, 2020).
gastric ulcer (continued). "This is in agreement with earlier reports that the root bark extract possesses anti-ulcerogenic properties in other induced gastric ulcer animal models and is supported by the inhibition of decrease of the anti-oxidative enzymes SOD, CAT and GPx." (PMID 23228052, 2012). "Moreover, AdipoRon administration reduced the CAT and increased SOD activity in the EtOH-induced gastric ulcer model." (PMID 34063466, 2021). "Gastric ulcers induced by ethanol had significantly decreased antioxidant enzyme activities (CAT and SOD) and non-enzymatic antioxidant (GSH), whereas pretreatment with Phy-Blica-D significantly improved the activities of CAT, SOD, and GSH." (PMID 35011049, 2021). "The ethanolic extract from M. maderaspatana was able to reduce gastric mucosal lesions, malondialdehyde (MDA) and TNF-α levels, while increased gastric juice mucin content and gastric mucosal catalase (CAT), nitric oxide and PGE2 levels in rats with indomethacin-induced gastric ulcer." (PMID 30018251, 2018). "The results in this study have not only reechoed the important relationship between SOD, CAT, and GSH levels and free radical induced oxidative stress in gastric tissues but have also provided evidence to support the ethnopharmacological relevance of Dissotis rotundifolia in managing gastric ulcer." (PMID 32318292, 2020). "In the present work, the significant inhibition of gastric ulcer formation observed in RBAEDM-treated animals could be justified in part by the significant (p < 0.001) decrease in MDA levels and the significant (p < 0.01, p < 0.001) increase in SOD and CAT activities." (PMID 40521211, 2025).
psoriasis (38 papers, 2015 to 2025). An autoimmune condition characterized by red, well-delineated plaques with silvery scales that are usually on the extensor surfaces and scalp. "Antioxidant enzymes, such as superoxide dismutase (SOD) and CAT, play a crucial role in reducing ROS levels, which are implicated in the pathogenesis of psoriasis." (PMID 40731925, 2025). "Noteworthy biomarkers such as myeloperoxidase (MPO), paraoxonase (PON), sirtuins (SIRTs), superoxide dismutase (SOD), and catalase (CAT) are emerging as key indicators of psoriasis pathogenesis and their association with mitochondrial ROS." (PMID 39456475, 2024). "Patients with psoriasis exhibit higher levels of advanced oxidation protein products and catalase compared to controls, with additional differences between genders supporting once more the need for a tailored therapeutical approach to each patient." (PMID 38255729, 2024). "Comprehending these regulatory processes is essential for interpreting the function of catalase in disorders like psoriasis." (PMID 39456475, 2024). "The characterization and utilization of oxidative stress indicators, including MPO, PON, SIRT, SOD, and CAT provide novel understanding of the development of psoriasis." (PMID 39456475, 2024). "The study found that psoriasis patients had significantly lower erythrocyte catalase activity (p < 0.001) compared to the control group." (PMID 39456475, 2024). "This review explores oxidative stress biomarkers and parameters in psoriasis, including myeloperoxidase, paraoxonase, sirtuins, superoxide dismutase, catalase, malondialdehyde, oxidative stress index, total oxidant status, and total antioxidant status." (PMID 39456475, 2024). "CAT activity was significantly higher in the control group in comparison to all groups of patients with psoriasis." (PMID 38540199, 2024). "Ultimately, understanding the complex correlation between catalase and psoriasis is crucial for developing efficient therapy strategies that specifically address oxidative stress and enhance antioxidant defenses in patients." (PMID 39456475, 2024). "A study assessed the plasma levels of CAT in 100 psoriasis patients and 100 healthy controls resulted in a significant reduction in CAT activity (p < 0.05) among individuals with psoriasis, suggesting the presence of oxidative stress in the condition." (PMID 39456475, 2024). "Higher level of AOPP and CAT were shown in patients with psoriasis as compared with healthy subjects." (PMID 38496030, 2024). "Maintaining optimal catalase activity is essential in psoriasis to mitigate the harmful effects of oxidative stress, thereby preserving skin integrity and reducing disease progression." (PMID 39456475, 2024). "Another study revealed significantly increased serum ROS like nitric oxide, malondialdehyde with decrease in the antioxidant activity of superoxide, catalase psoriasis patients compared to the control." (PMID 37531036, 2023). "According to our findings, the bioactivities of SOD and CAT in the vehicle-treated IMQ-induced psoriasis group were significantly lower than those in the naive group." (PMID 36556472, 2022). "We have recently shown the increased level of AOPP and CAT in patients with psoriasis vs. controls." (PMID 40821633, 2025). "Also, it reduces levels of malondialdehyde (MDA) and increases activity of superoxide dismutase (SOD) and catalase (CAT), which in turn reduces inflammation similar to psoriasis caused by imiquimod in mouse models." (PMID 40690118, 2025). "Superoxide dismutase and catalase are the most studied antioxidants in patients with psoriasis." (PMID 38399624, 2024). "Research suggests that psoriasis may lead to reduced CAT activity, which contributes to oxidative stress and may exacerbate the disease’s etiology." (PMID 39456475, 2024). "The link between CAT gene expression and psoriasis was also investigated." (PMID 39456475, 2024).